FSHR (follicle stimulating hormone receptor)
Diseases named in the same sentence as FSHR in open-access papers (continued):
Sharing a sentence is not in itself a finding about the gene and the disease.
breast cancer (16 papers, 2013 to 2025). A primary or metastatic malignant neoplasm involving the breast. "It has also been demonstrated that FSHR expression is associated with vascular remodeling in the endothelium of breast cancer." (PMID 33716953, 2020). "Endothelial FSHR expression in breast cancer is associated with vascular remodeling at tumor periphery." (PMID 25652007, 2015). "Transcriptional dynamics validation via qRT-PCR confirmed detectable expression of LHR and FSHR mRNA transcripts in all mammary specimens analyzed, including 14 physiological mammary controls and 37 mammary tumor tissues from canines." (PMID 40431589, 2025). "Our investigation revealed a marked downregulation of two key reproductive regulators—luteinizing hormone receptor and follicle-stimulating hormone receptor—in canine mammary tumors relative to normal mammary tissues." (PMID 40431589, 2025). "Compared to normal mammary tissues, the transcript levels of LHR and FSHR were markedly diminished in mammary tumor tissues (p < 0.001 and p < 0.001, respectively)." (PMID 40431589, 2025). "Targeting the tumor vasculature through the FSHR antibody was explored in breast cancer treatment for the first time, and the antibody helped GBNs enter breast cancer cells because targeting tumor blood vessels does not require extravasation." (PMID 34266419, 2021). "In our work, TOX3 promoted estrogen biosynthesis by upregulating genes related to the development of breast cancer, including FSHR, CYP19A1, and BMP6." (PMID 33716953, 2020). "In breast cancer patients, FSHR was expressed in endothelial cells and blood vessels at the tumor edge." (PMID 33329391, 2020). "All four molecular subtypes of breast cancer expressed almost similar densities of FSHR stained blood vessels." (PMID 25652007, 2015). "The FSHR+ vessels were exclusively located at breast cancer periphery, in a layer that extended 2 mm into and 5 mm outside of the tumor." (PMID 25652007, 2015). "In metastases of breast cancer to the lung pleura, the percentage of blood vessels expressing FSHR was positively correlated with the progesterone receptor level, but not with either HER-2 or estrogen receptors." (PMID 23688201, 2013). "FSHR expression has been identified in various cancer cells, but rarely in breast cancer tissues or cell lines." (PMID 24137476, 2013). "LHR and FSHR expression has been confirmed in human mammary tumor tissues and cell lines." (PMID 40431589, 2025). "Additionally, the results demonstrated that the transcript quantification of LHR and FSHR was lowest in grade 3 mammary tumor tissues, consistent with the immunohistochemistry results." (PMID 40431589, 2025). "Similarly, we detected LHR and FSHR expression in canine mammary tumor tissues, with distinct expression patterns correlated with spay status: LHR expression was upregulated in tumors from spayed dogs, whereas FSHR expression showed a downward trend." (PMID 40431589, 2025). "The ability of FSHR to activate Gαi/o signaling has been reported in both gonadal, and non-gonadal tissues including bone, adipose, and pathophysiological contexts such as endometriotic lesions and breast cancer tissue." (PMID 35185785, 2021). "In addition to Gαs, FSHR has been reported to couple and activate Gαi/o in both gonadal and extragonadal systems such as bone, adipose and breast cancer cells." (PMID 35185785, 2021). "In addition, we have shown that LHR and FSHR are also expressed in mammary tumors induced by NMU in rats." (PMID 29867771, 2018). "Conversely, mammary tumor tissues displayed heterogeneous expression of LHR and FSHR in the cytosolic regions of the neoplastic epithelium, with levels ranging from negative to strong expression." (PMID 40431589, 2025). "To understand the extragonadal regulation of LHR and FSHR in rat mammary tumors induced by NMU, we analyzed the expression of LHR and FSHR in rat ovary (internal control) and rat mammary tumors with immunohistochemistry." (PMID 29867771, 2018).
breast cancer (continued). "(All four clinical treatment groups of breast cancer we have analyzed (HR+/HER2- tumors, HR-/HER2+ tumors, HR+/HER2+ tumors, and TN breast tumors) expressed similar densities of tumor peripheral FSHR+ blood vessels)." (PMID 25652007, 2015). "Previous studies have shown that LH/FSH signaling through LHR/FSHR activates G protein-coupled ROCK–moesin and FAK–paxillin axes, significantly enhancing invasive pseudopod formation and transendothelial migration in breast cancer cells." (PMID 40431589, 2025). "Common among FSHR+ vessels, regardless of breast cancer type, were the high densities of arterioles and venules (6.4 ± 1.4 and 13.9 ± 2.1 vessels/mm2, respectively)." (PMID 25652007, 2015). "Notably, as the malignancy grade increased and differentiation decreased, the protein expression of LHR and FSHR significantly decreased, with minimal to no expression observed in grade 3 mammary tumors." (PMID 40431589, 2025). "Although FSHR expression has not been identified in primary tissues of breast cancer, high FSH levels have been associated with a significantly poor prognosis in patients with premenopausal breast cancer." (PMID 24137476, 2013). "FSH may function in the malignant transformation of breast cancer via a specific receptor, but not the traditional FSHR." (PMID 24137476, 2013).
ovarian failure (16 papers, 2011 to 2025). "This study was conducted to determine the FSH profile and FSHR polymorphisms in Madrasin cattle and Madura cattle experiencing ovarian hypofunction." (PMID 32636582, 2020). "Loss of function mutations and single nucleotide polymorphisms in follicle stimulating hormone receptor (FSHR) are also linked with ovarian failure by virtue of the gonadotropin resistance that accompanies these mutations." (PMID 30534420, 2018). "By contrast, among patients with RIF, many individuals may inherently harbor additional ovarian dysfunctions beyond those associated with the FSHR, thereby impairing the compensatory mechanisms that would otherwise support folliculogenesis and oogenesis." (PMID 40806494, 2025). "A study combining MD simulations with in vivo and in vitro data was performed to explore the mechanism of a novel mutant I423T targeting the follicle-stimulating hormone receptor (FSHR) and leading to primary ovarian failure." (PMID 40076272, 2025). "Nevertheless, some clinical conditions have been associated with increased FSH levels and FSH receptor (FSHR) activity, as result of ovarian failure in the menopausal period." (PMID 33802415, 2021). "Homozygous mutations in the follicle-stimulating hormone receptor (FSHR) are extremely rare, affecting mostly females with variable degree of pubertal development and complete ovarian failure." (PMID 31220230, 2019). "However, it is not possible to exclude the involvement of autosomal genes in the onset of ovarian insufficiency as some genes located on autosomes have been associated with the POF phenotype, for example INHA, FSHR and FOXL2." (PMID 22794123, 2012). "In addition, the genetic alterations of genes in signal transduction pathways with regard to FSHR function in granulosa cells in females with ovarian failure may contribute to changing the drug response and effects." (PMID 33561079, 2021). "The phenotype of FSHR (−/−) mouse, FORKO (follitropin receptor knockout), is a suitable model to study ovarian failure in humans." (PMID 22412875, 2012). "Moreover, because no variation was found, it was reported that the FSHR gene was not correlated with reproductive parameters, including ovarian hypofunction in Madrasin cattle." (PMID 37235159, 2023).
ovarian tumors (15 papers, 2012 to 2025). "The loss of FSHR in FORKO mice was associated with increased ovarian tumor development and an increased migration of epithelial cells into the ovaries compared to wild-type mice." (PMID 33374698, 2020). "As an example, Ji and colleagues found significantly higher levels of mRNA encoding receptor for FSH (FSHR) in invasive ovarian tumors compared to low malignant tumors and normal OSE." (PMID 26635885, 2016). "Therefore, confirming the role of FSH in ovarian tumors and its underlying mechanisms would be essential for further optimizing the clinical application of FSHR immunotherapies." (PMID 38505602, 2024). "It is anticipated that blocking FSH/FSHR and downstream signaling pathway via m6A alteration would provide a novel therapeutic avenue for ovarian tumor metastasis." (PMID 38505602, 2024). "Female mice developing PPNM-based ovarian tumors that inherently express the FSHR were intraperitoneally infused with CER T cells, and transferred T cells were sorted from tumor locations 7 days later based on the differential expression of congenic markers." (PMID 38168227, 2023). "In another study, anti-FSHR immune receptors were used to redirect T cells to ovarian tumors by inducing the expression of anti-FSHR immune receptors in the patient’s T lymphocytes." (PMID 28439256, 2017). "FSHR is highly expressed on ovarian tumors and involved with cancer development and metastatic signaling pathways." (PMID 26779384, 2015). "In this study, the goal is to determine the feasibility of imaging ovarian tumors based on the binding of BI-10 to FSHR in vitro and in vivo." (PMID 26779384, 2015). "This review seeks to determine whether the follicle-stimulating hormone receptor is expressed in ovarian tumor types and, therefore, is suitable as a target in a future theranostic approach." (PMID 38539473, 2024). "Notably, the TCE targeting FSHR was found to have high potency in attenuating tumor burden/tumor progression in vivo in an ovarian tumor–bearing mouse model." (PMID 36509287, 2022). "FSH and LH levels in the pituitary and plasma were significantly greater (up to 4-fold) in FORKO mice compared to wild-type mice suggesting that the absence of FSHR is associated with ovarian tumor development despite high gonadotropin levels." (PMID 33374698, 2020). "FSHR is expressed in ovarian tumors (64.3% analyzed samples)." (PMID 30778333, 2019). "Finally, certain cancers, prominently ovarian tumors in which oncogenic signaling through the FSHR can be proven may be amenable to novel FSH-based therapeutic agents." (PMID 30941099, 2019). "In human specimen, we also confirmed that FSHR, ALKBH5 and Snail protein expression showed significant upregulation in ovarian tumors, compared to normal ovarian tissue, m6A content in total mRNA was higher than those in ovarian tumors." (PMID 38505602, 2024). "Upregulation of FSHR, ALKBH5, Snail was observed in ovarian tumor." (PMID 38505602, 2024). "Evaluation of different FSHR-expressing ovarian tumor cells demonstrated that D2AP11-TCE was highly efficient in the killing of CAOV3, OVCAR3-FSHR, OVCAR4, OVISE, PEO-4, and Kuramochi-FSHR cells." (PMID 36509287, 2022). "They argued that FORKO mice have high circulatory levels of FSH and LH, ovarian androgens are elevated, estrogens are very low, no FSHR and still have high incidence (>90%) of ovarian tumors by 12 months of age." (PMID 23509758, 2013).
premature ovarian failure (15 papers, 2012 to 2026). "Examination of the first amino acids in extracellular loop 1 showed that substitutions at Asp405, Thr408, and Lys409 abolished cAMP synthesis, and the inactivating FSHR mutations Asp224Val and Leu601Val led to impaired cAMP production in a heterozygous patient with premature ovarian failure." (PMID 32992880, 2020). "Mutations in the FSHR gene have been reported as a cause for primary ovarian failure (POF)." (PMID 22412875, 2012). "We examined SNPs in FSHR, INHA, ESR1, and BMP15, which have been associated with primary ovarian failure." (PMID 37239044, 2023). "In the mouse model of cyclophosphamide-induced premature ovarian failure, we found that FSHR mRNA expression was significantly decreased." (PMID 38076111, 2023). "The occurrence of FSHR, INHA, ESR1, and BMP15 gene polymorphisms has also been reported to be associated with various reproductive diseases, including primary ovarian insufficiency (POI), pregnancy loss, and preeclampsia." (PMID 37239044, 2023). "Our findings confirm previous reports of mammalian FSHR mutations that caused primary ovarian insufficiency and elevated cAMP levels without agonist treatment." (PMID 32992880, 2020). "This study analyzed whether the small-molecule FSHR agonist CAN1405 rescued membrane expression and function of 13 mutant FSHRs leading to premature ovarian failure in women." (PMID 41988939, 2026).
male infertility (14 papers, 2013 to 2024). The inability of the male to effect fertilization of an ovum after a specified period of unprotected intercourse. "Then in the meta-analysis, a significant association was seen between FSHR rs6165, rs6166 polymorphisms and male infertility." (PMID 28764642, 2017). "In this study, we found that significant heterogeneity existed in overall analysis and sub-group analysis for the comparison of FSHR rs1394205 polymorphisms and male infertility." (PMID 28764642, 2017). "To date, no clear consensus appears to have been reached in the literature on the relationship between FSHR polymorphisms and male infertility risk." (PMID 28764642, 2017). "Previous studies examining potential associations between FSHR polymorphisms and male infertility parameters have produced contradictory results." (PMID 28764642, 2017). "Thereby, we conclude that there is a lack of the association between common genetic variants in the FSHR gene and substantial effect on male infertility risk." (PMID 24718625, 2014). "Several studies have been produced and analyzed in the present review in order to understand which markers are prognostic of a good response to FSH treatment in male infertility, such as spermatid count, testicular cytology, and the assessment of the polymorphisms in both FSHR and FSHB genes." (PMID 39202711, 2024). "Meta-analysis across the Baltic cohort and Estonian male infertility group reached statistically highly significant association between the FSHR Ser680 variant and reduced total testes volume (p = 0.000066, resistant to Bonferroni correction for multiple testing; effect = −1.40 mL)." (PMID 23413141, 2013). "However, previously- reported meta-analyses including our meta-analysis considered 188 men with normozoospermia and 285 fertile men as controls, which brought out different associations between the FSHR rs1394205A allele and male infertility, resulting in the significant heterogeneity." (PMID 28764642, 2017). "Autosomal genes, e.g., the CFTR gene (located on chromosome 7) and the FSH receptor (FSHR) gene (located on chromosome 2), have been shown to cause male infertility." (PMID 37174664, 2023). "A prospective longitudinal study was conducted on 42 patients with idiopathic male infertility, 23 of whom underwent to FSHR c." (PMID 32498268, 2020). "Then the most common FSHR allelic variants in the core promoter and exon 10, and the FSHB variants in the core promoter were genotyped with respect to male infertility status using the Mass ARRAY platform." (PMID 28764642, 2017). "Several polymorphisms have been shown to correlate with specific types of male infertility, including polymorphisms in the number of CAG repeats in exon 1 of the androgen receptor (AR), FSHR, estrogen receptor (ER) α, and gr/gr deletions in the AZFc gene." (PMID 25653674, 2015). "Several human genes are known with mutations causing male infertility (AR; AZF gene families; CFTR, DM-1, DNAH gene family, FGFR1, FSHR, INSL3, KAL-1, LGR8-GREAT, LHR, POLG)." (PMID 26097523, 2015). "No statistical difference was detected in allelic distribution of the FSHR Asn680Ser between the Baltic cohort and Estonian male infertility group." (PMID 23413141, 2013). "Common FSHR polymorphisms in exon 10 and the promoter of FSHR have been extensively studied in male infertility but there is no clear association of male infertility with FSHR SNPs so far." (PMID 34717708, 2021). "However, the associations between these SNPs in the FSHR gene and FSHB and male infertility remain uncertain." (PMID 28764642, 2017). "Furthermore, homozygous FSHR mutations lead to male infertility in few cases, while the A189V FSHR mutation in males is linked with subfertility but not azoospermia." (PMID 34367061, 2021).
male infertility (continued). "In terms of male infertility with multifactorial etiology, further studies with larger sample sizes and different ethnic backgrounds or other risk factors are warranted to clarify the potential role of FSHB and FSHR polymorphisms in the pathogenesis of male infertility." (PMID 28764642, 2017). "Indeed, to date having molecules able to bias signaling at the FSHR represent important pharmacological tools to understand the specific FSHR signaling pathway contributing to different pathologies both in women and men, such as PCOS and male idiopathic infertility." (PMID 37305033, 2023).
Azoospermia (13 papers, 2012 to 2025). Absence of any measurable level of sperm,whereby spermatozoa cannot be observed even after centrifugation of the semen pellet. "In humans, FSHβ mutations lead to azoospermia and infertility, although men with mutation in FSHR are phenotypically normal with some subfertility, similar to deficient mice with the same mutation." (PMID 34576272, 2021). "In humans, fertility phenotypes in carriers of inactivating FSHB or FSHR mutations varies from azoospermia to mild reduction of spermatogenesis." (PMID 30619093, 2018). "Men carrying loss-of-function mutation in the gene encoding the ligand (FSHB) or its receptor (FSHR) present, respectively, with azoospermia or suppressed spermatogenesis." (PMID 30619093, 2018). "The present study aimed to investigate the correlation between two FSHR SNPs at positions A919G, A2039G, and susceptibility to azoospermia in a group of Iranian azoospermic men." (PMID 26730241, 2015). "The results of the present study indicated that the genetic polymorphisms in the FSHR gene might increase the susceptibility to azoospermia in Iranian men." (PMID 26730241, 2015). "In primates, restricted FSHR signalling by the infant Sertoli cells may cause azoospermia." (PMID 26730241, 2015). "In humans, distinct fertility phenotypes, ranging from azoospermia to oligozoospermia, have been described in carriers of the FSHB or FSHR mutations, respectively." (PMID 34884539, 2021). "The mutant FSHR reversed the azoospermia and partially restored fertility of Lhr–/– mice." (PMID 29584617, 2018). "However, there are only a few publications regarding the relationship between FSHR SNP and azoospermia." (PMID 26730241, 2015). "The rare FSHR mutations described in men suggest they lead to subfertility with testosterone levels within the physiological range and reduced spermatogenesis, but not necessarily to azoospermia." (PMID 32260182, 2020). "In this study, two SNPs of FSHR gene at positions A919G and A2039G were genotyped and the relationship with azoospermia was investigated in 212 azoospermic patients (126 non-obstructive and 86 obstructive) and 200 healthy Iranian men." (PMID 26730241, 2015). "However, the absolute lack of FSH or FSHR, despite a reduction in Sertoli cell number, does not lead to azoospermia nor sterility." (PMID 32260182, 2020).